EGFR (epidermal growth factor receptor)
Diseases named in the same sentence as EGFR in open-access papers (continued):
Sharing a sentence is not in itself a finding about the gene and the disease.
cancer (continued). "Mutations in key proteins of Wnt and EGFR pathways have been found in most of the cancers." (PMID 20828404, 2010). "In cancers, mutations or dysregulation in the Wnt pathway often induce EGFR activation." (PMID 20828404, 2010). "However, recently there have been reports of the presence of EGFR somatic mutations in H and N cancers, albeit at a low incidence (1–14%)." (PMID 21274259, 2010). "EGFR-mutation is one of the most frequent genetic changes found in human cancers." (PMID 20498858, 2010). "The incidence of EGFR mutations in H and N cancer in this study was 5.3%." (PMID 21274259, 2010). "Taken together, these findings are striking and show another facet of the cell evolution landscape, highlighting the possibility of cancer cells resisting targeted treatment to molecules such as HER2 or EGFR by acquiring oncogenic mutations in downstream pathways." (PMID 20604919, 2010). "EGFR was the first RTK to be directly linked to human cancers." (PMID 19563658, 2009). "Importantly, overexpression of EGFR and/or its ligands is frequently observed in human cancers, and recent studies have identified activating mutations in EGFR as direct determinants of oncogenic transformation in human cancers." (PMID 19948031, 2009). "For example, the L858R mutation in EGFR is a common mutation in cancer and is classified as an activating mutation, but its effect is a result of the mutation destabilizing the inactive conformation of the enzyme and causing it to fold into an active conformation even in the absence of ligand." (PMID 20011534, 2009). "EGFR overexpression has been associated with an aggressive clinical course in many cancers." (PMID 19747398, 2009). "Deregulation of the EGFR/ERK pathway due to alterations affecting the expression or function of a number of pathway components has long been associated with numerous forms of cancer." (PMID 19804630, 2009). "Some recent studies have implicated a role of STAT3 and EGFR in mediating EMT in cancer cells." (PMID 19088723, 2009). "Because it has been previously reported that poor differentiation is associated with unfavourable outcome in other cancers, the association between EGFR expression and poor differentiation may also be a reason that EGFR expression is a prognostic factor." (PMID 18087285, 2008). "Although, it remains controversial as to whether EGFR overexpression is the cause of the cancer or a secondary consequence, the strong association between the EGFR and cancer has made it a natural candidate as an anti-cancer chemotherapeutic." (PMID 21892266, 2008). "Gefitinib and erlotinib are orally active EGFR-TKIs that block signal transduction pathways implicated in the proliferation and survival of cancer cells and other host-dependent processes promoting cancer cell growth." (PMID 16911776, 2006). "Consistently, nuclear accumulation of EGFR correlates with increased expression of cyclin D1, inducible nitric oxide synthase (iNOS) and B-Myb, all of which are frequently overexpressed in human cancers and associated with increased cell proliferation." (PMID 16434982, 2006). "EGFR was the first tyrosine kinase receptor to be directly linked with human cancer." (PMID 16280056, 2005). "Furthermore, the interaction between MUC1 and EGFR may partially promote drug resistance by activating the IL-6 signaling pathway, which is implicated in cancer stem cell enrichment and subsequent chemotherapy failure." (PMID 40655139, 2025). "Therefore, inhibiting autophagy may increase the susceptibility of certain cancers, including EGFR-mutant cancers, to immunotherapeutics." (PMID 40940888, 2025). "Extensive research has led to the characterization of the structure and signaling of EGFR, identification of its mutations and gene amplification, definition of its role in cancer development, and consequently, the development of tyrosine kinase inhibitors as anti-cancer therapies." (PMID 39966897, 2025).
cancer (continued). "Notably, EGFR is frequently overexpressed or mutated in various epithelial malignancies, making it one of the most clinically validated molecular targets for precision cancer therapy." (PMID 41155547, 2025). "Moreover, this approach may prove effective in treating cancers with overexpression or mutation of specific downstream targets of EGFR." (PMID 40859900, 2025). "Therefore, the CBL and MAPK3 changes observed in this study may reflect a rebalancing of EGFR signaling that can lead to inhibition of cancer cell growth, even in the presence of KRAS mutations." (PMID 41226554, 2025). "Whether ICBs are suitable for cancer patients with EGFR mutations remains to be explored." (PMID 40859900, 2025). "Moreover, the results of the present study suggest that CIN-dependent activation of cGAS–STING signaling may contribute to cancer cell proliferation under EGFR-TKI treatment in a subset of EGFR-mutated NSCLC tumors." (PMID 40136696, 2025). "Thus, this study is the first to show that SMARCB1-deficient tumors resist EGFR-TKIs in cancer." (PMID 39971779, 2025). "Thus, whether the therapeutic and diagnostic values of CAP rested on EGFR uncovered here are extensible to other cancer types requires intensive pre-clinical validation and clinical evidence." (PMID 39781456, 2025). "Several molecular mechanisms related to MET acquired resistance as well as genetic aberrations or phenotypic changes could contribute to cancer progression during treatment with EGFR-TKIs, leading to the loss of EGFR expression with the inability of TKIs to work efficiently." (PMID 38611009, 2024). "Therefore, suppressing endogenous Reg IV expression or inhibiting Reg IV/EGFR signaling may have the potential as a novel therapeutic tool to prevent dysplasia and cancer associated with UC." (PMID 39421174, 2024). "Moreover, EGFR overexpression and phosphorylation, which are common mechanisms in epithelial malignancies, are associated with metastasis, chemotherapy resistance, and poor prognosis, making it a promising target for cancer therapy." (PMID 38592437, 2024). "Among patients with EGFR-positive NSQ cancer, subtypes were exon-19 deletion (2999 patients [43.7%]), exon-21 L858R substitution (2591 patients [37.7%]), T790M (556 patients [8.1%]), exon-20 insertion (185 patients [2.7%]), and other EGFR variants (535 patients [7.8%])." (PMID 38334998, 2024). "Similarly, the EGFR modulation could cause alterations in the phosphoinositide-3-kinase-Akt-mammalian target of rapamycin (PI3K-Akt-Mtor) signaling pathway to fostering cancer cell survival." (PMID 38799236, 2024). "Although a number of studies have now shown value of an EGFR-AURKA combination in EGFR-mutated or -overexpressing cancers, the question of whether this combination may have activity in lung tumors that do not contain EGFR driver mutations has not been addressed." (PMID 38639476, 2024). "To determine whether the EGFR mutations included in the target regions of the ODxTT and AmoyDx panel corresponded to therapeutic mutations, we referred to the Clinical Interpretation of Variants in Cancer (CIViC) and OncoKB databases." (PMID 38238401, 2024). "In addition to harbouring EGFR mutations, cancer cells may also evade treatment by constitutively activating downstream effectors in an EGFR-independent manner." (PMID 38615034, 2024). "We used this information and examined whether treatment with an EGFR inhibitor, osimertinib, which is already approved for clinical use in cancer therapy, can reduce the infection caused by SARS-CoV-2, wild type, and Omicron and Delta variants, in two cell lines and one spheroid model." (PMID 39291996, 2024).
cancer (continued). "However, it’s unclear how these EGFR mutations contribute to cancer treatment resistance." (PMID 38689087, 2024). "Although FGFR3 mutation presumably initiated cancer development in these cancers, it has been suggested that at some point during tumor progression, EGFR signaling may have increased to a level where it repressed mutant FGFR3 expression and dominated the downstream signaling." (PMID 39031286, 2024). "Moreover, even when PD-L1 expression is high, those harboring EGFR mutations may still respond less favorably to immunotherapy compared to the general cancer patients." (PMID 39062533, 2024). "Thus, the appearance of multiple primary EGFR-mutant tumors is biologically distinct from the metastatic spread of cancer and it may result from an initiating EGFR mutation, either in the germline or during early development." (PMID 39406916, 2024). "However, aberrant activation, gene mutation, or increased ligand expression of the EGFR signaling pathway may result in sustained activation, which is closely associated with invasion, metastasis, and poor prognosis in many malignant tumors." (PMID 39796003, 2024). "However, if some common and rare EGFR mutations are in the same cancer cells, they might interfere with the response to certain EGFR TKIs." (PMID 36829178, 2023). "Changes to the EGFR gene (overexpression of receptor, dysregulation or mutation, amplified expression of EGFR binding ligands), however, can lead to continual or abnormal activation of the receptors, causing unregulated cell division that causes various types of cancers." (PMID 41551238, 2023). "The precise mechanism may be associated with the role of RBM38 and GAS5 in EGFR activation, c-Jun activation, autophagy, protein kinase B activation, formation of a hypoxic environment, dysregulation of apoptosis, cancer stem cell renewal, and epithelial–mesenchymal transition." (PMID 37296859, 2023). "The high immunogenicity of commonly shared EGFR mutations implied that vaccinating against these EGFR mutations may be a potential strategy in treating cancers harboring these mutations, or preventing cancer recurrence after EGFR TKI therapy." (PMID 37766136, 2023). "Also, EGFR’s expression served as a powerful diagnostic and prognostic indicator for cancer." (PMID 36893122, 2023). "In addition, cancer cells also acquired resistance to post-monoclonal antibody therapies via EGFRvIII overexpression, mutations, and activation of downstream signaling pathways; mutations in the extracellular domain; and EGFR heterodimerization." (PMID 38137520, 2023). "In addition, IL-1RA-promoted OSCC malignancy involved enhanced properties of cancer stemness via a mitochondrial metabolism-associated EGFR/JNK pathway, which may be suppressed by application of mitochondrial complex inhibitors both in vitro and in vivo." (PMID 37461111, 2023). "In addition, EMT is associated with EGFR-TKI resistance in EGFR-mutated cancers." (PMID 36841821, 2023). "However, mutations in EGFR have been found to cause cancer cells to be resistant to these drugs." (PMID 37587470, 2023). "Therefore, accurate and disease-relevant diagnostic methods may leverage the detection of EGFR levels in cells to identify carcinomas in their early stages." (PMID 37444523, 2023). "Here, we performed a targeted sequencing panel of 324 cancer‐related genes (including ABL1, BCL2, CDH1, EGFR, etc.)at an average depth of 500× in all the specimens to identify mutations in genes that may be pivotal for synchronous primary cancer (BioProject accession number: PRJNA761143)." (PMID 36128740, 2022).
cancer (continued). "In GBM constitutive EGFR activation due to mutations or gene amplification causes deregulated proliferation, angiogenesis, and inhibition of apoptosis; for this reason, bypassing the apoptotic pathway to induce cancer cell death can be considered a promising approach to overcoming this problem." (PMID 35393392, 2022). "Thus, we hypothesized that among several pre-existing cancer cell clones carrying different resistance mechanisms, some resistant cell clones that expand shortly after EGFR-TKIs would eventually cause the resistant phenotype." (PMID 35326664, 2022). "Thus, we investigated whether resistant cancer cells that expand shortly after EGFR-TKI treatment would eventually cause the resistant phenotype." (PMID 35326664, 2022). "Hence, considering that most cancer patients are already susceptible to electrolyte disturbances as well as dehydration secondary to cancer, further studies on risk stratification with appropriate management measures are warranted to improve patient outcomes from EGFR inhibitor therapy." (PMID 35954563, 2022). "The pharmacophore model-based drug discovery together with the molecular lab-based studies might be useful to facilitate extensive research for other scientists on EGFR mutation through targeting other EGFR-related carcinomas and can be able to find new candidates with a lower toxicity profile." (PMID 36457709, 2022). "Since IL-1 can also trigger cancer cell death, the linked tumorilytic and acnegenic effects of EGFR blockade in such patients could reflect the same mechanism: namely, loss of negative feedback by (active) EGFR, leading by default to bypass upregulation of FGFR2b." (PMID 34007277, 2021). "Therefore, mutations that cause overexpression of EGFR are associated with a number of cancers." (PMID 34502049, 2021). "Furthermore, EGFR is associated with HPV-related cancer prognosis." (PMID 34646755, 2021). "Additionally, patients receiving EGFR-TKIs could be immunocompromised and have a higher risk of infection because of advanced cancer, which can lead to a wrong diagnosis." (PMID 33466795, 2021). "Because EGFR has been the pioneer member of the receptor tyrosine kinase family, and many lines of evidence linked this receptor, its growth factor ligands, and co-receptors to human malignancies, EGFR research has paved the way to several important concepts in cancer progression." (PMID 34206026, 2021). "Two protein domains on EGFR, namely Furin-like domain and growth factor receptor IV domain on EGFR, also had comparably large positive coefficients (deleterious), although somatic mutations on these domains of EGFR were observed in specific cancers with much lower frequencies (14 of 33 types)." (PMID 34254998, 2021). "Aberrant signaling by EGFR (ErbB1) and ErbB2, caused by gene amplification, deletions in the extracellular domain, activating kinase domain mutations, or ligand coexpression, drives the progression of many human cancers, especially in the breast, lungs, and colon." (PMID 34572289, 2021). "Besides, COLI induces EGFR-TKI resistance in EGFR-mutated cancer cells." (PMID 34976811, 2021). "Therefore, it is thought that HE4 may influence the biological behaviour of cancer cells in the ovaries through the EGFR and MAPK signalling pathways; however, the specific underlying mechanism is still unclear." (PMID 34107979, 2021). "Discovering molecular mechanisms of how EGFR activity and E-cadherin-mediated adhesion co-exist in normal tissues is essential for understanding the causes of the amplifying feedback between them in cancer cells and developing approaches to break this feedback." (PMID 35127732, 2021). "Therefore, inhibiting IL-6 could be helpful to cancer patients receiving EGFR-TKI treatment to reduce the risk of side effects." (PMID 34976811, 2021).
cancer (continued). "However, further studies are needed to clarify whether JAC1 is also effective against HER2 or EGFR mutations, as well as the drug resistance of related cancer cells." (PMID 33875644, 2021). "We used publically available data from the cancer cell line encyclopaedia (CCLE) database to search for mutations in EGFR, ERBB2, ERBB3, ERBB4, KRAS and BRAF that might predispose to a different response to anti-HER2 therapies or PI3K or MAPK pathway inhibition." (PMID 33933113, 2021). "In addition, miR‐7 could target numerous oncogenic genes in cancer‐associated pathways, such as EGFR,37PIK3CD,38Ack139 and Raf1,40 indicating the significant suppressive roles in cancers." (PMID 34551195, 2021). "Nevertheless, subsequent studies demonstrate that patients with sensitizing mutations of EGFR gene are more responsive to gefitinib or erlotinib compared with patients without such mutations, which leads to the administration of EGFR inhibitors for precision cancer therapy." (PMID 34419139, 2021). "Moreover, exosomes could be internalized by EGFR-mutated cancer cells via Clathrin-dependent endocytosis and then the encapsulated exosomal wild type EGFR protein activated downstream PI3K/AKT and MAPK signaling pathways and triggered osimertinib resistance." (PMID 33461557, 2021). "In addition to the EGFR signaling change, there were also changes in several cancer‐associated proteins, such as vimentin; the marker of epithelial‐to‐mesenchymal transition (EMT) was upregulated in PC3 knockdown cells and the EMT regulator β‐catenin was upregulated upon EWI‐2 knockdown." (PMID 33605506, 2021). "Interestingly, activation of EGFR signaling pathway plays important roles in radiosensitivity of cancer cells as irradiation induces unusual activation of EGFR signaling and thus causes radioresistance through EGFR activation-controlled cell proliferation, DNA repair, hypoxia, and metastasis." (PMID 33869036, 2021). "In addition, although we described that there was a significantly higher EGFR mutation rate and other unique mutation features of cancer driver genes in the NSCLC patients, the majority of them were early stage (175 patients in stage I) which is still unnecessary to undergo targeted therapy." (PMID 32657049, 2020). "EGFR is a receptor tyrosine kinase that plays fundamental roles not only in physiology but also in cancer, its overexpression and/or mutations have been found in many cancers which may affect the development and progression of cancer 1-4." (PMID 32127953, 2020). "Some cancer patients may develop therapeutic resistance to anti-EGFR therapy in the presence of EGFRvIII variant due to reduced affinity of the mAbs raised against the wild-type EGFR." (PMID 35047986, 2020). "Therefore, identifying mutations in EGFR may greatly assist treatment for several different cancers." (PMID 32059456, 2020). "However, after withdrawal of the drug, the reemergence of clonal EGFRvIII mutations on DMs effectively resensitized cancer cells to EGFR inhibitors, which could then induce cell death." (PMID 32928268, 2020). "In this study, EGFR mutation detection was possible if 1.5% of carcinoma cells were included, but detection was also possible by cytology if the cancer cell content was 0.1% since background cells such as inflammatory cells and debris could be removed from the specimen." (PMID 32033355, 2020). "Since the most common EGFR-independent resistance mechanisms involve reactivation of RTK/RAS/effector pathways, we wanted to assess whether inhibition of different proteins within the EGFR/RAS signaling pathway could synergize to inhibit 3D survival of EGFR (T790M) mutated cancer cells." (PMID 32897190, 2020). "The EGFR-c-Raf-MEK and PTEN-mTOR-Akt signaling pathways are closely associated with cancer cell properties, and we therefore suggest that the modulation of EGFR-c-Raf-MEK and PTEN-mTOR-Akt by RPE could be the underlying mechanism responsible for RPE’s anti-cancer activity." (PMID 33158043, 2020).